JAK2 (Janus kinase 2)
Diseases named in the same sentence as JAK2 in open-access papers (continued):
Sharing a sentence is not in itself a finding about the gene and the disease.
tumor (continued). "Collectively, these data support the assertion that miR-204-5p has key tumor suppressor functions in HNSCC that are largely determined by its ability to silence SUZ12, SNAI2, JAK2 and HDAC1, and thus inhibit clinically aggressive tumors." (PMID 31938073, 2020). "Research on the detailed mechanisms of this process showed that CCc proliferation occurs through an IL-6/JAK2/STAT3-dependent mechanism and VEGF-induced tumor angiogenesis." (PMID 32429087, 2020). "In the present study, we found that an IL-17a neutralizating antibody partly suppressed the JAK2 or STAT3 phosphorylation, which suggested that IL-17a partially contributed to the tumor-promoting effects of TANs on GC cells." (PMID 30616627, 2019). "Our findings support the notion that a unique oncogenic JAK2 mediates the degradation of FOXO3 protein and contributes to an understanding of the control of FOXO3 protein in the tumor." (PMID 31540495, 2019). "In vivo, EREG expression in stroma fibroblasts promoted tumor growth with high stromal α-SMA, phospho-JAK2/STAT3, and IL-6 expression and upregulated EMT in HSC3 cells." (PMID 31234944, 2019). "Taken together, the results demonstrated that miR-126 exerts tumor suppressing effects on the proliferation, migration and invasion by inhibiting MMP2, MMP9 and JAK2/STAT3 pathway via targeting ZEB1." (PMID 31007650, 2019). "Actually, the JAK2 selective inhibitor, fedratinib decreased the cellular proliferation of HL and PMBCL cell lines, and reduced tumor growth in murine xenograft models of cHL and MLBCL with 9p24.1/JAK2 amplification." (PMID 31707975, 2019). "Thus, activation of the JAK2/STAT signaling pathway could promote tumor growth in HL." (PMID 31707975, 2019). "Subsequently, the abundances of p-STAT5, STAT5, p-JAK2, JAK2, and SOCS2 proteins were measured in tumor tissues." (PMID 30988277, 2019). "LincRNA-p21 acted as a tumor suppressor in HNSCC progression, which was attributed to direct binding to STAT3 and blocking of JAK2/STAT3 signaling." (PMID 30857539, 2019). "TAMs-derived IL6 activated the JAK2/STAT3 pathway, and activated STAT3 transcriptionally inhibited the tumor suppressor miR-506-3p in CRC cells." (PMID 30927925, 2019). "The Janus kinase 2 (JAK2) leads to activation of the signal transducer and activator of transcription (STAT) pathway, which can also be activated by cytokines from the tumor microenvironment and by a gain of chromosome 9p." (PMID 31707975, 2019). "BMA secrete abundant IL-6, which induces the epithelial-mesenchymal transition in tumour cells via the JAK2/STAT3 pathway, and strengthens the metastatic potential of tumour cells via PI3K/AKT." (PMID 31334678, 2019). "For example, miR-375 inhibits CRC cell proliferation mainly through targeting both JAK2/STAT3 and MAP3K8/ERK signaling pathways, miR-30a regulates cell proliferation and tumor growth of CRC by targeting CD73, miR-374b regulates CRC cell apoptosis." (PMID 31998373, 2019). "Additional confidently classified W-ex mutations from the cell line data that were noted to act in a similar manner as LDHB and have been shown to positively influence tumor progression are BCLAF1, JAK2, and KMT2D49–51." (PMID 31484939, 2019). "We showed that TFRG were able to downregulate the levels of iNOS via JAK2/STAT3 signal pathway which were highly expressed and activated in tumor tissues." (PMID 29951107, 2018). "Combined treatment with paclitaxel and momelotinib inhibited paclitaxel-induced JAK2/STAT3 activation and CSC-like development in mice xenografts, and consequently reduced the tumor burden significantly greater than that achieved by paclitaxel-treatment alone." (PMID 29682172, 2018). "Leptin activated the downstream Jak2/STAT3 signaling in LepR(+) tumor cells, which led to enhanced proliferation, survival and migration of tumor cells." (PMID 30013512, 2018).
tumor (continued). "FDTN contributed to the downregulation of the JAK2/STAT3 signaling pathway, and thus reversed the ELTN resistance to enable enhanced anti-tumor efficacy both in vitro and in vivo." (PMID 30483119, 2018). "Previous studies have shown that JAK2/STAT3 signaling regulates several important pathways in tumorigenesis, including cell cycle progression, apoptosis, tumor invasion, and metastasis." (PMID 29515107, 2018). "TFRG also markedly reduced tumor mass of MDA-MB-231 xenografts with inhibition of iNOS and formation of nitrotyrosine by JAK2/STAT3 signaling pathway." (PMID 29951107, 2018). "The Janus kinase 2/signal transducer and activator of transcription 3 (JAK2/STAT3) signaling pathway is activated in numerous types of tumors and regulates cell proliferation, angiogenesis, and migration of tumor cells." (PMID 30285793, 2018). "Reg3g produces these effects by activating the JAK2/STAT3 signaling pathway in DCs, triggering the generation of an immunosuppressive tumor microenvironment." (PMID 28880262, 2017). "Taken together, these results demonstrated that CAFs promoted tumor growth in vivo by inducing EMT and activating JAK2/STAT3 pathway." (PMID 29100297, 2017). "Immunohistochemistry of tumor tissues showed that SKLB-850 efficiently inhibited the activation of Syk/ERK, Src/FAK and JAK2/Stat3 pathways." (PMID 29340070, 2017). "In vitro, Reg3g upregulated EGFR in DCs, activated heme oxygenase-1 (Hmox1) involved JAK2/STAT3 signaling, raised levels of Th2 cytokines in and suppressed maturation of DCs, and enhanced tumor cell proliferation." (PMID 28880262, 2017). "The JAK2/STAT5, PI3K/AKT and MEK/ERK signaling pathways are frequently altered in tumor cells and evidence that EPO induces these signal transduction cascades is accumulating." (PMID 28418910, 2017). "By contrast, natural killer (NK) cell activation and secretion of IFN-γ significantly enhanced PD-L1 expression by activating JAK1, JAK2, and STAT1 in tumor cells." (PMID 27974689, 2017). "QRHX inhibited tumor cell-TAMs interactions via the suppression of cancer-related inflammation and probably blocking the response of macrophages to tumor signals, CXCL12/CXCR4/JAK2/STAT3 axis." (PMID 28630636, 2017). "In gene level, oncogenic signaling pathways in tumor cells, such as IFN-γ/JAK2/IFN, ALK/STAT3, PI3K, and MEK/ERK/STAT1 can activate PD-L1 expression." (PMID 27974689, 2017). "To define the role of JAK2 in the prometastatic effect of JAKi, we used the JAK2i BSK805 in tumour-bearing mice." (PMID 27406745, 2016). "Emerging research has suggested that the tumor promoting and metastatic activity of mucin-16 (CA125) is involved in the JAK2 signaling pathway." (PMID 27081079, 2016). "Since Janus kinases (JAKs) mediate STAT3 activation in tumor angiogenesis, we first tested the effect of VEGFA on Jak1 and Jak2 tyrosine phosphorylation in HRMVECs." (PMID 27210483, 2016). "Growing evidence suggests that JAK2/STAT3 signaling can be activated by IL-6 and this activation is required for tumor initiation and progression." (PMID 27367272, 2016). "Our previous finding demonstrated that SSM2 and SSM3 cells display persistent prolactin receptor signaling with activation of JAK2, STAT3 and STAT5A/5B, and that pharmacological inhibition of pJAK2 increased SSM2 and SSM3 tumor cell apoptosis." (PMID 27391074, 2016). "For instance, IL-6 expression activates signalling through Janus kinase 2 (JAK2) and Stat3, EGF increases the concentration of pre-oncogenic phosphorylated Akt, whereas CXCL12 and CCL5 stimulate tumour growth through the PI3K-Akt-mTOR pathway." (PMID 27845732, 2016). "JAK2/ STAT3 signaling regulates several important pathways in tumorigenesis including cell cycle progression, apoptosis, tumor invasion, and metastasis." (PMID 26755649, 2016). "The results showed that treatment with combination of BSN and paclitaxel strongly inhibited constitutive p-JAK1, p-JAK2, and p-Src in NSCLC tumor tissues." (PMID 25788267, 2015).
tumor (continued). "Consistent with HEY cell line, addition of CYT387 resulted in the inhibition of phosphorylation of JAK2 and STAT3 in paclitaxel-induced ascites-derived tumor cells (Ascites 9–11), while the expression of T-JAK2 and T-STAT3 remained unchanged." (PMID 24886434, 2014). "In small cell lung cancer, CXCL12 can stimulate JAK2/STAT3 constitutive phosphorylation, which is important in tumor cell growth and spreading." (PMID 25405202, 2014). "In order to elucidate this, the JAK2/STAT3 signaling pathway was downregulated in the present study, as IL-6 and STAT3 work together in the tumor microenvironment to promote several cancer hallmarks, for example increased proliferation, survival and invasion." (PMID 24527098, 2014). "Our observation of STAT5 phosphorylation in PCM1-JAK2 cells contingent upon JAK2 activity strongly suggests that both translocations operate via STAT5, supporting a paradigm of STAT5 activation in JAK2-neoplasia." (PMID 23372669, 2013). "A high-level CCND3 tumor (Case OC-07) showed co-amplification of MYC and AKT2; and a high-level MYC tumor (OC-08) was co-amplified for JAK2, FGFR3, and MYB." (PMID 23289505, 2013). "Some reviews published in the literature have already pointed out and discussed the relationship between constitutively activated JAK2/STAT signaling and deregulation of apoptosis-related genes in CML and human tumor cell lines." (PMID 22300941, 2012). "Silencing JAK1, JAK2 or TYK2 using RNA interference (RNAi) inhibits FGF2-mediated proliferation and results in the sensitization of tumor cells to chemotherapy-induced killing." (PMID 21625473, 2011). "Our data here indicate that JAK2 and STAT3 are activated by the cytokine OSM and that this cytokine is present in canine patient tumor samples." (PMID 21481226, 2011). "Given that OSM is present in all canine patient tumor samples, it is plausible to infer that OSM in the tumor microenvironment in vivo likely enhances OSA basal Src and STAT3 activation and JAK2 phosphorylation." (PMID 21481226, 2011). "These properties are of importance based on recent murine studies showing the Jak2 inhibitor WP1193 can augment immunotherapy with IFN-α, and STAT3 siRNA-CpG oligodeoxynucleotides can elicit anti-tumor immune responses." (PMID 20576164, 2010). "Intriguingly, tyrosine kinase JAK2 and a member of cell contact-mediated communication CELSR3 were found to be selectively up-regulated in tumor stellate cells." (PMID 20416094, 2010). "In addition, JAK2 blockade favors the selection of resistant clones that reactivate JAK/STAT signaling and drive tumor progression." (PMID 41463071, 2025). "To investigate the potential mechanism of tumors in HFD mouse, we found that HFD mouse could activate the phosphorylation of JAK2, STAT3, and NF-κB p65 protein in TNBC tumor tissue." (PMID 40841364, 2025). "Given the strong anti-tumor efficacy of CD19 CAR-T cells in REH cells, we hypothesized that a more challenging model would be suitable for evaluating the effects of JAK2 inhibitors on CD19 CAR-T cells." (PMID 39891728, 2025). "Evaluation of gene expression can provide insightful information about the tumor microenvironment.Until now, to our knowledge, the JAK2/STAT3/CTLA4 axis has not been investigated for tissue-specific gene expression at the mRNA levels in OSCC." (PMID 40092547, 2025). "Furthermore, tumor-secreted LCN2 can bind to SLC22A17 on tumor cells, activating JAK2/STAT3 signaling and promoting VEGF-A expression and release, which enhances tumor neovascularization." (PMID 41436606, 2025). "Additionally, in lung cancer (A549) cells, UA inhibits the JAK2/STAT3 pathway, reducing cancer stem cell marker expression and tumor stem cell populations, which sensitizes these cells to cisplatin [1050]." (PMID 40490812, 2025). "Previous studies found that the JAK2/STAT3 pathway activates the apoptosis inhibitors survivin, Mcl-1, Bcl-2, and Bcl-XL to block the caspase cascade and the initiation of apoptotic mechanisms in tumor cells." (PMID 40519928, 2025).
tumor (continued). "As MSN contains a FERM domain identically found in JAK2 and IL-6 stimulates hyperactivation of JAK signaling, we next examined whether IL-6 acts on tumor cells to activate MSN." (PMID 40696387, 2025). "Targeting both JAK2 and PI3KCD simultaneously can potentially overcome the limitations of single-agent therapies by blocking multiple survival and proliferation signals, thereby reducing tumor growth and metastasis." (PMID 39735669, 2025). "In conclusion, our results suggest that hypoxia-induced suppression of UPF1 expression decreases NMD efficiency, leading to the stabilization of COX-2 and PD-L1 mRNAs, thus activating the p38/MAPK and JAK2/STAT3 pathways and promoting tumor progression in NPC cells." (PMID 41293174, 2025). "Notably, JAK2/STAT3 signaling supports CSC self‐renewal, which is crucial for tumor recurrence and resistance to treatment." (PMID 41049266, 2025). "As a result, niche edits show no propagation with neighbor copying: perturbing tumor periphery spots to the normal state leaves predictions for adjacent Jak2 KO spots unchanged under kNN, even though cross-niche signaling should modulate their expression." (PMID 41292874, 2025). "In TNBC, the interactions between molecules or co-regulatory networks, such as NF-κB may simultaneously participate in the regulation of MMP9 and TNFα, while JAK2 may form cross-pathways with PI3K/Akt, jointly affecting tumor progression." (PMID 40356970, 2025). "Since JAK–STAT3 activation promotes macrophage recruitment, M2 polarization, and immunosuppression during tumor progression, we hypothesized that ITGA2hi‐PTC regulates M2 polarization via JAK2/STAT3 signaling." (PMID 40985182, 2025). "Furthermore, STAM2 significantly influences the expression of MMP2/MMP9, as well as the phosphorylation of JAK2/STAT3 in cancer cells, thereby enhancing tumor malignancy." (PMID 40149859, 2025). "In cHL, Pleiotrophin activates JAK2/STAT6, contributing to immune evasion and tumor plasticity." (PMID 41438753, 2025). "In the microenvironment of HB, the activation of the JAK2/STAT3 pathway promotes tumor angiogenesis by increasing the expression of angiogenic factors such as vascular endothelial growth factor (VEGF), which is crucial for tumor growth and metastasis." (PMID 41393242, 2025). "Treatment with an STAT3-specific activator partially reversed the tumor-suppressive effects of APOC2 knockdown, supporting the hypothesis that JAK2/STAT3 is a key downstream effector of APOC2." (PMID 41296440, 2025). "Notably, CHZ868 demonstrated synergistic anti-tumor effects with CD19 CAR-T cells, even in JAK2 wild-type B-ALL cells." (PMID 39891728, 2025). "One study found that IGF2BP2 may work to promote tumor growth in PTC via interactions with APOE mRNA and the IL-6/JAK2/STAT3 pathway." (PMID 40243425, 2025). "In the mouse model, luteolin effectively inhibited tumor growth and downregulated the expression of phosphorylated JAK2 and STAT3 without altering the total protein levels of JAK2 and STAT3." (PMID 40051568, 2025). "Our experiments found that after Neo-BCV treatment, only the phosphorylation levels of JAK2 and STAT3 in mice subcutaneous tumor tissues were significantly affected, indicating that Neo-BCV specifically inhibits the phosphorylation of JAK2, thereby suppressing the activation of STAT3." (PMID 39852843, 2025). "Its mechanisms of action involve apoptosis induction, immune system modulation, and disruption of key oncogenic signaling pathways, including the inhibition of glucose transport via GLUT1 and suppression of JAK2/STAT3 signaling, thereby impeding tumor growth and metastasis." (PMID 40761486, 2025). "Mice were treated with JAK2 and STAT3 inhibitors to assess immune and tumor responses." (PMID 40384867, 2025).
tumor (continued). "For example, lactate in the tumor microenvironment epigenetically upregulates the expression of VSIG4 in macrophages, which subsequently activates the JAK2/STAT3 pathway, enhances fatty acid oxidation and PPAR-γ expression, and drives polarization toward an immunosuppressive M2 phenotype." (PMID 40873588, 2025). "In tumor tissues, there was a moderate correlation between IL-6 and STAT3 (r = 0.449, P < 0.001), whereas a weak correction between IL-6 and gp130 (r= 0.314, P = 0.002), as well as JAK2 (r = 0.230, P = 0.028)." (PMID 38881895, 2024). "We also found that circUBA2 could upregulate STC1 expression via miR-144-5p sponging and further activates the IL-6/JAK2/STAT3 signaling pathway, thereby promoting stemness and tumour progression in GC in vivo and in vitro." (PMID 39103836, 2024). "Moreover, the IHC staining also confirmed that METTL3, p-JAK2/p-STAT3, GLUT1, and Ki67 were significantly elevated in the mice tumor with injection of MHCC97H mixed with Exo-incubated macrophages or M2 macrophages." (PMID 39247822, 2024). "However, when miR-9 and miR-218 downregulated the expression of IL-6 and Janus kinase 2 (JAK2), they inhibited the activation of STAT3, leading to the downregulation of STAT3 expression and thus inhibiting the growth of tumor cells." (PMID 38172648, 2024). "Mechanistic investigation demonstrated that FXR specifically bound to the promoters of IL-6ST and IL-6 genes to upregulate their transcription, thereby leading to activation of the Jak2/STAT3 signaling pathway, which facilitated tumor migration, invasion, and angiogenesis in NSCLC." (PMID 38360812, 2024). "For example, a 2013 study showed that the inhibition of JAK2 using TG101209 and the inhibition of both JAK1 and JAK2 with INCB18424 in leukemic mice substantially decrease tumor size and improve survival outcomes, which are antecedents of the acquisition of genetic alterations." (PMID 38273387, 2024). "The abnormally activated IL-6/JAK2/STAT3 signaling pathway can contribute to the onset and progression of malignant tumors by affecting the proliferation, migration, invasion, angiogenesis, and apoptosis of tumor cells." (PMID 38881895, 2024). "Treatment with the potent JAK1/JAK2‐specific inhibitor, ruxolitinib, significantly reduces tumor burden; however, ruxolitinib treatment does not fully eradicate the malignant clone." (PMID 38104968, 2024). "Interestingly, the role of SOCS5, SOCS6, JAK2/STAT3, and PI3K/AKT pathways in DDP resistance of tumor cells has been well documented." (PMID 38439876, 2024). "In in vivo models of JAK dependent malignancy, itacitinib impedes subcutaneous tumor growth of INA-6 cells expressing wild type JAKs when administered by continuous infusion, achieving plasma concentrations well below those necessary to inhibit JAK2." (PMID 38380328, 2024). "CMTM family proteins also exert their biological functions by signaling pathways that correlate with cell growth and migration, including the EGFR, WNT and JAK2/STAT3 signaling pathways, indicating that CMTM proteins are potential targets for altering tumor progression and metastasis." (PMID 38223763, 2024). "Similarly, in tumor cell implantation (TCI) models, the upregulated levels of microglial p-JAK2 and p-STAT3 proteins in the spinal cord horn are involved in the development and maintenance of cancer-induced bone pain (CIBP)." (PMID 37307838, 2024). "Notably, IL-6 can elevate the levels of EIF4A3 and CCL2 in tumor cells via activation of the JAK2/STAT3 pathway, further facilitating tumor cSERPINE2 biogenesis and inducing TAMs recruitment." (PMID 38397395, 2024). "Additionally, the CCL18/PITPNM3 axis has been shown to activate the JAK2/STAT3 signaling pathway, a conserved pathway involved in tumor growth and metastasis." (PMID 39409924, 2024).